INS (insulin)
Diseases named in the same sentence as INS in open-access papers (continued):
Sharing a sentence is not in itself a finding about the gene and the disease.
Hyperglycemia (continued). "Moreover, insulin levels were elevated in early overnutrition pups relative to control but were no longer elevated by adulthood, even in the face of hyperglycemia, suggesting a failure of beta-cells to properly respond to increased metabolic demand." (PMID 34234216, 2021). "Therefore, if SGLT2i combined with medical nutrition therapy can promptly lower BG levels without SU or a high dose of insulin, the treatment would be safe and effective for acute stroke patients with hyperglycemia." (PMID 35050147, 2021). "Interestingly, hyperglycemia per se does not contribute to Myc-induced β-cell apoptosis since blood glucose normalization by insulin treatment or islet transplantation in these transgenic mice does not prevent nor reduce β-cell loss." (PMID 33239359, 2021). "In this group, low insulin levels have not corelated with significant hyperglycemia, improved beta-cell functioning in response to elevated blood glucose might have contributed for the blood glucose lowering effect." (PMID 34353691, 2021). "However, hyperglycemia is often difficult to control in the CKD population, as several antihyperglycemic agents are contraindicated in CKD patients, and the pharmacokinetics of others, including insulin, change with declining glomerular filtration rate." (PMID 34441977, 2021). "To test our hypothesis, we generated insulin-deficient mice lacking LEPRs in RIP-Cre25Mgn neurons (RIP-CreΔLEPR) and examined whether i.c.v. leptin injection can lower hyperglycemia in these mice without insulin." (PMID 33071988, 2020). "Furthermore, it has been demonstrated that the effects of anti-inflammatory and organ protection gained from insulin in scalded experimental rats without controlling hyperglycemia." (PMID 33679687, 2020). "We can speculate that despite attenuation of GSIS, the multifunctional properties of V. opulus still would be able to decrease, at least partially, postprandial hyperglycemia regardless of insufficient or inappropriate insulin secretion." (PMID 32429334, 2020). "This could explain why insulin targeting of hyperglycemia on admission aimed at stroke neuroprotection does not provide significant clinical benefit." (PMID 33255770, 2020). "This is probably because beta-cell destruction is so rapid that insulin in the destroyed beta-cells may enter the blood stream within a short period of time and then resulted in hyperglycaemia without sufficient regulations of more insulin." (PMID 32149155, 2020). "The hypothesis was that IM administration of insulin lispro is safe in treating canine DKA and that resolution of hyperglycemia, ketosis, and acidemia would be equally fast or faster in dogs treated with IM insulin lispro compared to dogs treated with IVCRI of regular insulin." (PMID 33195532, 2020). "GLP-1 receptor agonists (GLP-1RAs), a new type of hypoglycemic drug, can not only increase insulin secretion, suppress appetite, and control weight by activating GLP-1 receptors, they can also control hyperglycemia by inhibiting glucagon secreted by islet α cells." (PMID 33194785, 2020). "The best characterized CPR is cephalic phase insulin release (CPIR), the release of a small amount of insulin in response to the presence of sweet taste stimulus in the oral cavity, which leads to attenuated postprandial hyperglycemia in humans, irrespective of BG levels." (PMID 32353974, 2020). "In addition, AMPK-mediated hyperglycemia to insulin signal transduction was not present in our data, which needs more evidence to complete the antidiabetic mechanism by WSP-L." (PMID 32425738, 2020). "Second, this study being observational, we could not describe the potential effect of insulin on the prevalence of hyperlactatemia and on the correlation between hyperlactatemia and hyperglycemia and/or oxygen extraction." (PMID 32656170, 2020).
Hyperglycemia (continued). "Differences in the SST inputs into GHRH neurons and plasma GH responses between 2DG and insulin suggest these responses may be related to effects of insulin or peripheral hyperglycemia rather than glucose deprivation." (PMID 33148883, 2020). "Afterwards, insulin-treated βRapKOGFP mice (euglycemic βRapKOGFP) maintained normoglycemia for 4 weeks, with comparable blood glucose levels as that of WT mice, whereas untreated mutant mice (diabetic βRapKOGFP) exhibited severe hyperglycemia." (PMID 32439909, 2020). "Hyperglycemia in obese CHF animals could have resulted from impaired insulin action in non-skeletal muscle tissues including liver and adipose tissue, or from differential metabolic alterations in different skeletal muscle groups." (PMID 33158222, 2020). "This shows that insulin does not constitute an important factor in the pathogenesis of hyperglycaemia at point of admission in most neonates, but it may be elevated as a compensatory mechanism to reduce the blood glucose back to normal." (PMID 32637004, 2020). "The early downregulation of liver Igf1 expression without affecting plasma glucose levels suggested a hyperglycemia-independent suppression of liver Igf1 mRNA expression in this model, likely due to the hypoinsulinemia resulting in decreased insulin signaling in the liver." (PMID 33004691, 2020). "By stimulating insulin release from pancreatic β-cells, with immediate consequences of increased glucose uptake from skeletal muscles, raised GLP-1 levels may in turn limit postprandial hyperglycemia." (PMID 32726990, 2020). "However, it has been reported in both human and rodent studies that normalization of hyperglycemia by insulin administration did not improve neurological outcome after traumatic brain injury." (PMID 33510613, 2020). "If the function of B cells was deteriorating at this time, thus showing hyperglycemia, then the cells could not compensate for insulin resistance." (PMID 32596376, 2020). "In addition, insulin is no longer able to inhibit gluconeogenesis, especially by the liver, thereby contributing to the progressive worsening of hyperglycemia." (PMID 33665204, 2020). "Also, this view fails to realize the potential double-edged role of insulin in treating hyperglycemia while driving the non-glycemic diseases of T2D." (PMID 32128655, 2020). "IDegAsp may also not be the preferred choice for steroid-induced hyperglycaemia, especially when steroid doses are rapidly changing, given the long duration of the insulin degludec component." (PMID 32290465, 2020). "Diabetic mice displayed mild hyperglycemia, increased duration and frequency of AF episodes vs. age-matched controls (e.g., AF duration: 19.7 ± 6.8 s vs. 1.8 ± 1.1 s, respectively, p = 0.032), whereas insulin-treated diabetic animals did not." (PMID 32903422, 2020). "Ad-EGFP-CaV3.1-transduced islets released significantly less insulin under both the basal and first phases following glucose stimulation and could no longer normalize hyperglycemia in recipient rats rendered diabetic by streptozotocin treatment." (PMID 31871187, 2020). "The animal study will include the following 6 groups (10 animals per group): sham; hyperglycemia without IS; IS without hyperglycemia; IS and hyperglycemia without treatment; IS and hyperglycemia and intravenous insulin; and IS and hyperglycemia and subcutaneous insulin." (PMID 33148277, 2020). "There is therefore a plausible mechanism by which direct fetal exposure to glyburide and stimulation of fetal insulin secretion could result in fetal overgrowth and adiposity, even in the absence of maternal hyperglycaemia." (PMID 32442232, 2020). "Lastly, the activation of the hexosamine biosynthetic pathway via hyperglycaemia could bring about the overexpression of a number of cytokines such as TGF-α, TGF-β, VEGF, and PDGF in non-insulin-sensitive tissues and also lead to the onset of diabetic complications." (PMID 32148647, 2020).
Hyperglycemia (continued). "Lack of insulin and hyperglycemia developed in this animal model could be due to partial damage of pancreatic β-cells via the cytotoxic action of STZ and block of insulin receptors by a high-fat diet." (PMID 32106580, 2020). "Notably, these changes were demonstrated to be related mostly to impaired insulin signaling and not hyperglycemia itself." (PMID 33419247, 2020). "Indeed, IR knockout results in hyperglycemia, but also in protecting from non-glycemic diseases of T2D, implying an obligatory role for insulin and IR in driving the non-glycemic diseases of T2D." (PMID 32128655, 2020). "While further studies are needed to examine the detailed effect of NPC43 on insulin secretion from the pancreas, our results clearly demonstrated that NPC43 is an effective oral and injectable agent for the treatment or mitigation of hyperglycemia in insulin-resistant T2D subjects." (PMID 31378829, 2020). "Furthermore, the effect of treat-to-target insulin on outcome in GC-induced hyperglycemia has not been shown." (PMID 33348743, 2020). "Our results showed that daily oral intake of Betula extract counteracted the STZ-induced hyperglycemia, without modifying blood glucose levels in non-diabetic rats and slightly but significantly increased insulin levels in diabetic rats after just one week of administration." (PMID 32927638, 2020). "Islet function, as evaluated by the capability to secrete insulin under conditions of high glucose, was improved in islets isolated from both male and female offspring of NAC-treated mice, suggesting a better adaptive response of β cells to conditions of hyperglycemia." (PMID 32183232, 2020). "Notably, transient hyperglycaemia and triglyceride/high-density lipoprotein cholesterol (TG/HDL) ratio may be useful tools for the identification of insulin metabolism impairment behind PTDM." (PMID 32258163, 2020). "Since all of them converge to show that altering insulin signalling does not alter steady state glucose levels, the insulin resistance and inadequate compensation hypothesis for steady state hyperglycaemia stands clearly rejected." (PMID 33365205, 2020). "Finally, we did not assess the effects of hyperglycemia and insulin therapy on intracellular signaling." (PMID 32993618, 2020). "One report analyzed 43 episodes of severe hyperglycemia ([Glu] > 33.3 mmol/L or 600 mg/dL), treated with insulin and no other interventions, in patients on chronic dialysis with no or minimal fluid intake and urine loss and no change in body weight during treatment." (PMID 32984372, 2020). "It is characterized by hyperglycemia with the irregular metabolism of carbohydrates, proteins, fats, and electrolytes due to a lack of insulin or the insensitivity of target cells to insulin, which results the elevation of blood sugar, leading to hyperglycemia." (PMID 30682840, 2019). "Thus, the effects of IOE to ameliorate hyperglycemia and adiposity may be mediated through FGF21 activating insulin signaling and increasing the expression of GLUT4 and pro-thermogenic factors." (PMID 31323977, 2019). "Our patient showed no signs of rebound hyperglycemia and required infrequent insulin boluses." (PMID 32025979, 2019). "Activation of protein kinase A elicited by the binding of incretins to their respective receptors cannot initiate the release of preformed insulin secretory granules from ß-cells, without closing of potassium channels, depolarization, and calcium ion influx, as determined by hyperglycemia." (PMID 31412576, 2019). "No data is available on the efficacy of prokinetic drugs in T1DM patients with mild alterations of GE rate; in the meanwhile, in these patients there is no way to handle PP hyperglycemia other than to adopt the insulin regimen that best matches their PP glucose profile." (PMID 31295897, 2019). "In addition, postprandial hyperglycemia developed and his severe glycemic fluctuations were not reduced by switching basal insulin from detemir to degludec and glargine." (PMID 30621663, 2019).
Hyperglycemia (continued). "Moreover, diabetic models are mainly (STZ) induced, which are not always able to attain complete insulin depletion, making the vanadium therapeutic efficacy dependent on the severity of hyperglycemia and residual insulin in the pancreas." (PMID 30350272, 2019). "Although the T2D monkeys were hyperglycemic, their insulin levels were unchanged, suggesting that the hyperglycemia may arise via a mechanism independent of insulin resistance." (PMID 31555072, 2019). "In addition, the path coefficient of hsCRP → insulin (β2 = 0.152, p = 0.009) was significant in the hyperglycemia group, but not significant in the normoglycemia group (β2 = 0.088, p = 0.121)." (PMID 31443647, 2019). "Patients should apply manual boluses by using a bolus calculator and CGM data but reaching post-meal normoglycemia without subsequent hyperglycemia or hypoglycemia due to insulin under-correction or over-correction, respectively, is difficult even for the most advanced algorithms." (PMID 31126048, 2019). "This lack of increased insulin secretion can facilitate hyperglycemia." (PMID 32133067, 2019). "Hence, to rule out insulin-dependent effects, the same oral gavage experiment was performed in inducible Kir6.2-p.Val59Met mice, which develop hypoinsulinaemia and hyperglycaemia." (PMID 30426168, 2019). "Interestingly, glucose and insulin levels were not affected by the diet but remained stable representing mild hyperglycemia in the E3L.GK+/− and GK+/− mice (10.4 ± 1.4 mmol/L and 14.1 ± 2.6 mmol/L at the end point, respectively)." (PMID 30949516, 2019). "Hyperglycaemia and hypergalactosemia occur after feeding in patients with FBS as a result of the defective transport and decreased uptake of monosaccharides by the liver, and hyperglycaemia is further aggravated by decreased glucose-stimulated insulin secretion in pancreatic beta-cells." (PMID 31137773, 2019). "Moreover, phlorizin corrected the dysregulation of glucagon secretion resulting from chronic hyperglycemia but did not affect the hypersecretion of insulin." (PMID 30415925, 2019). "It is important to match insulin dose with extra CHO intake as excessive carbohydrate supplementation without matched insulin may result in hyperglycemia." (PMID 31258513, 2019). "We postulated that insulin, not hyperglycemia, promoted ApoL1 secretion in the Mets liver." (PMID 31619724, 2019). "Therefore, hyperglycemia may stimulate the secretion and release of CILP-2, as hyperglycemia promotes insulin release." (PMID 30896018, 2019). "When IR progresses to T2DM, the lack of insulin signaling molecules is common as hyperglycemia." (PMID 31920677, 2019). "Finally, acarbose, an α-glucosidase inhibitor that improves insulin sensitivity and decreases postprandial hyperglycemia, does not inhibit fructose transport in human Caco-2 cells or in Xenopus oocytes expressing the mammalian GLUT2 and GLUT5." (PMID 31905727, 2019). "Leptin infusion or gene therapy, can reverse hyperglycemia without a detectable rise in circulating insulin levels in STZ-treated rats and mice, non-obese diabetic (NOD) mice, insulin deficient Akita mice and BioBreeding rats with virally-induced beta cell destruction." (PMID 31231496, 2019). "However, it has recently been reported that insulin antibodies occasionally result in characteristics similar to those due to insulin autoantibodies in IAS patients, including marked glycemic fluctuations with postprandial hyperglycemia and fasting hypoglycemia." (PMID 30621663, 2019). "The treatments of VEGF only reverse the weight loss of testes and epididymis, suggesting that the mechanism of hyperglycemia-induced reproductive dysfunction associated with VEGF level, but VEGF can not affect insulin secretion, which is the main factor to control diabetic rats body weight." (PMID 29435181, 2018).
Hyperglycemia (continued). "Moreover, unlike control animals, the mutant mice failed to adequately increase basal insulin levels upon overnutrition, resulting in hyperglycemia and progressive glucose intolerance when exposed to this challenge." (PMID 29864031, 2018). "d-serine mediated hyperglycemia is independent of insulin sensitivity." (PMID 30093356, 2018). "However, insulin release is reduced (not shown) and consequently the establishment of hyperglycemia, confirming decreased insulin serum concentration and elevated serum glucose in diabetic animals in this study (DM)." (PMID 29796316, 2018). "However, differently from ASE treatment, a decrease of hyperglycemia induced by exercise training alone was not dependent on the reduction of high insulin levels, which is in agreement with a previous study." (PMID 29920546, 2018). "A lack of insulin secreted by the pancreatic beta cells can lead to hyperglycaemia." (PMID 30046337, 2018). "Although currently available therapeutic strategies including various oral agents and exogenous insulin can ameliorate hyperglycemia or temporarily improve insulin sensitivity, none of them can actually reverse the progressive and inexorable β-cell function damage." (PMID 29988034, 2018). "Furthermore, LepRbHtr2cKO mice exhibited neither hyperglycemia nor alteration in serum insulin or leptin concentrations." (PMID 29914853, 2018). "Adherence problems may not only affect heart failure patients, some of the observed readmissions were also due to non-adherence regarding insulin, resulting in hypo- or hyperglycemia." (PMID 29337859, 2018). "This could suggest that even a slight decrease of insulin concentration, which was not detectable in the analysis, may result in hyperglycaemia or there could have been other factors affecting the increase of glucose concentration." (PMID 29743097, 2018). "Furthermore, amylase and/or amylase derivatives could enhance glucose uptake in insulin-independent tissues such as enterocytes via GLUT1 or GLUT2, and in this case could serve as a defensive mechanism against the development of hyperglycemia." (PMID 30293998, 2018). "Whey protein ingestion reduces postprandial hyperglycemia without increases in C‐peptide release or insulin concentrations suggesting that whey may affect glucose clearance by stimulating insulin‐independent mechanisms." (PMID 30510711, 2018). "Males from cluster 2 showed intermediate levels of glucose with 136 ± 49 mg/dl and insulin concentrations of 18 ± 10 ng/ml which is consistent with an intermediate condition of hyperglycemia and hyperinsulinemia between nondiabetic and diabetic animals from clusters 1 and 3, respectively." (PMID 29854816, 2018). "Our findings from insulin-pelleted βEedKO animals, as well as from our mosaic/normoglycemic Pdx-EedKO mice, demonstrate that PRC2-associated dedifferentiation is cell autonomous and does not require hyperglycemia." (PMID 29754954, 2018). "On the other hand, hyperglycemia induced by lack of insulin promotes diuresis." (PMID 29619008, 2018). "Strikingly, a significantly higher percentage of insulin+ cells were detected in 9-day and 16-day, but not in 23-day, 30-day and 60-day grafts implying that hyperglycemia could only facilitate NPCC-derived β cells early post-Tx." (PMID 29844347, 2018). "Subcutaneous rapid- or short-acting insulin before meals or every 4–6 h may be used in patients not on regular meals or in patients receiving continuous enteral/parenteral nutrition to correct hyperglycemia." (PMID 29508275, 2018). "Unfortunately although hyperglycemia could result from decreases in insulin sensitivity, insulin levels were not reported." (PMID 29743868, 2018). "For example, the generation of the hypothesis “there is not enough insulin” requires that the hypothesis “patients have hyperglycemia” be true and its activation requires the registration of insulin self-collected health data." (PMID 30291097, 2018).